TNF (tumor necrosis factor)
Diseases named in the same sentence as TNF in open-access papers (continued):
Sharing a sentence is not in itself a finding about the gene and the disease.
rheumatoid arthritis (continued). "Pro-inflammatory mediators contained with IL-1β, TNF-α, and PGE2 can also enhance the binding activity of NF-κB with Nurr1 promoter, thereby promoting Nurr1 transcription and elevating Nurr1 mRNA and protein level in primary rheumatoid arthritis and normal synoviocytes." (PMID 32477062, 2020). "ADA, antidrug antibody; BP, biopharmaceutical product; IBD, inflammatory bowel disease; IFN, interferon; IL, interleukin; IM, intramuscular; MS, multiple sclerosis; RA, rheumatoid arthritis; SC, subcutaneous; TNF, tumor necrosis factor." (PMID 33125391, 2020). "TNF inhibitor drugs are a treatment option for rheumatoid arthritis, but response is not universal." (PMID 33124499, 2020). "Clinical trials provided metabolic beneficial effects of anti-TNF-α agents (infliximab, etanercept, adalimumab, golimumab, and certolizumab pegol) or IL-6 inhibitor (tocilizumab) on HbA1c, insulin resistance and insulin sensitivity in T2DM patients with psoriasis or rheumatoid arthritis." (PMID 32471207, 2020). "Chronic inflammation may lead to several inflammatory disorders including sepsis, rheumatoid arthritis, asthma, diabetes and Crohn’s disease and involves production and secretion of various pro-inflammatory cytokines including IL6, TNF and high mobility group box-1 (HMGB1)." (PMID 30947238, 2019). "Natural killer cells in rheumatoid arthritis patients were reduced upon IFX therapy and in ulcerative colitis patients derived cells, IFX treatment decreased the proliferation of CD4+ and CD8+ T-cells as well as their secretion level of IFNγ and TNFα, among other cytokines." (PMID 31272418, 2019). "B cell activating factor (BAFF), a member of the tumor necrosis factor (TNF) family, plays a critical role in the pathogenesis and progression of rheumatoid arthritis (RA)." (PMID 31240234, 2019). "In patients with the autoimmune disease rheumatoid arthritis, it is the MBCs that have the highest levels of LFA-1 and VLA-4; moreover, compared with healthy donors, naïve B and MBCs of patients receiving anti-TNF medication have enhanced levels of the active form of LFA-1." (PMID 30949178, 2019). "HS exerted treatment effects on RA by regulating 4 core targets (CSF2, IL1β, TNF, and IL6), which involved in 15 pathways such as rheumatoid arthritis, TNF signaling pathway, and cytokine-cytokine receptor interaction." (PMID 31885670, 2019). "However, most of the previous studies on TNF antagonism focused on the inflammatory cases and particularly on rheumatoid arthritis; consequently there are no experimental studies on breast cancer in this context." (PMID 31239840, 2019). "Overexpression of TNF results in a severe chronic inflammatory arthritis in collagen-induced arthritis (CIA) mice, an animal model of rheumatoid arthritis (RA)." (PMID 29725328, 2018). "There have been reports that inhibiting the inflammatory response induced by IL-1β and TNF-α had protecting effect on OA progress in surgical mouse model of OA, and anti-inflammatory drugs, such as COX-2 inhibitor and diacerein, can be the common treatment for both rheumatoid arthritis and OA." (PMID 29784003, 2018). "Here we set out to identify a predictive biomarker that discriminates rheumatoid arthritis (RA) patients who are more likely to develop ADA in response to adalimumab, a human monoclonal antibody against tumor necrosis factor (TNF)α." (PMID 30568660, 2018). "In rheumatoid arthritis (RA) patients, culturing of CD4+CD28+ T cells with TNFα results in the reduction of CD28 expression on CD4 cells and generation of the CD4+CD28null subset by influencing CD28 gene transcription." (PMID 29546695, 2018). "Notably, the result obtained using the Kyoto Encyclopedia of Genes and Genomes (KEGG) pathway analysis revealed a highly significant association of inflammatory diseases such as cytokine–cytokine receptor interaction, TNF signal pathway, Jak-STAT signaling pathway, rheumatoid arthritis and IBD." (PMID 29773794, 2018).
rheumatoid arthritis (continued). "Whilst such approaches have been very effective for certain diseases [e.g., anti-TNF-α monoclonal antibodies for the treatment of rheumatoid arthritis (RA)] a large percentage of patients either do not respond to treatment or become refractory to therapeutic antibody treatment." (PMID 29209334, 2017). "Recent studies using a p110δ-selective inhibitor in a mouse model of rheumatoid arthritis showed that p110δ plays an anti-inflammatory role in synoviocytes through inhibition of Akt/PKB activation, induced by platelet-derived growth factor and tumour necrosis factor α (TNFα)." (PMID 28851839, 2017). "In addition, ASMCs from chronic cough patients showed evidence of reduced inflammatory pathway stimulation, such as the TNFα, JAK-STAT and chronic inflammation (rheumatoid arthritis and inflammatory bowel disease) pathways compared with cells from healthy non-cough subjects in response to poly(I:C)." (PMID 28842514, 2017). "PGRN levels are elevated in the synovial fluid of patients with rheumatoid arthritis (RA), osteoarthritis (OA), and other arthropathies 4, 5, 6, and PGRN has been shown to inhibit TNF‐induced osteoclastogenesis and promote osteoblast differentiation in mice." (PMID 27428882, 2016). "The AhR protein expression was up-regulated in the presence of TNF-α and smoking and exposure to TCDD enhanced rheumatoid arthritis (RA) inflammatory processes in synovial tissue from RA patients." (PMID 27520027, 2016). "Eighteen patients with rheumatoid arthritis and secondary Sjögren’s syndrome not responding to conventional treatment were recruited for treatment with infliximab, a monoclonal antibody against TNF-α." (PMID 27259576, 2016). "Although inhibition of TNF-alpha is a proven therapeutic concept in patients suffering from rheumatoid arthritis and psoriasis, no clinical benefits could be observed using anti-inflammatory drugs in patients with CHF yet." (PMID 27822484, 2016). "TNF-α is a key cytokine in the inflammatory response and is a potential target for therapeutic strategies related to ALI, as it is known that patients suffering from an inflammatory response, such as rheumatoid arthritis and Crohn’s disease, will benefit from blocking TNF-α." (PMID 26990441, 2016). "In rheumatoid arthritis (RA), a positive proinflammatory feedback loop was found, where HMGB1 induces release of TNF-alpha from activated macrophages, which in turn induces translocation to the cytosol in macrophages." (PMID 26854151, 2015). "Similarly, amelioration of insulin sensitivity was noted in non-diabetic patients with rheumatoid arthritis receiving TNF-α antagonist therapy." (PMID 26633680, 2015). "In patients with rheumatoid arthritis, the number of Tregs can be normal; however, these cells may not be effective in decreasing TNF-α release." (PMID 26312490, 2015). "The tumor necrosis factor alpha (TNF) antagonists are a relatively new class of drugs used to treat multiple inflammatory diseases, including rheumatoid arthritis (RA)." (PMID 25141123, 2014). "Importantly, research into T cells in rheumatoid arthritis has led to novel treatments to treat this disease such as the TNF-α inhibitor, etanercept and IL-6 antagonist tocilizumab which inhibit or neutralize TNF-α and IL-6 respectively." (PMID 25501574, 2014). "Although clinical application of anti-TNF-α therapy has not been established in the treatment of human NASH, anti-TNF-α neutralizing antibodies are effectively used to treat various human inflammatory disorders, such as rheumatoid arthritis and inflammatory bowel diseases." (PMID 24849253, 2014). "The tumor necrosis factor alpha (TNF-α) is a proinflammatory cytokine involved in the pathogenesis of many inflammatory and autoimmune conditions as rheumatoid arthritis (RA) and inflammatory bowel disease among others." (PMID 24707429, 2014).
rheumatoid arthritis (continued). "Infliximab, a monoclonal antibody to TNF-alpha, which neutralizes TNF-alpha and down-regulates the expression of granulocyte-macrophage colony-stimulating factor has been demonstrated to be an effective therapy for Crohn's disease, rheumatoid arthritis and other Th1-mediated disorders." (PMID 24321021, 2013). "The authors showed in rheumatoid arthritis-derived Treg cells that Ser418 was specifically dephosphorylated by protein phosphatase 1 (PP1), whose expression and enzymatic activity ca be induced by tumor necrosis factor α (TNF-α) leading to impaired Treg-cell function." (PMID 24350059, 2013). "Similar to the findings of the current study demonstrating invariant TRP/CAA ratio after treatment with anti-TNF-α, it was shown adalimumab, which is also a TNF-α antagonist, exerts its immune-suppressant effect without influencing IDO activity and TRP levels in patients with rheumatoid arthritis." (PMID 23544139, 2013). "The three TNF-α antagonists (etanercept, infliximab, and adalimumab) appear to have similar efficacy in rheumatoid arthritis (JIA), but this does not appear to be the case with uveitis where infliximab seems to be more effective than etanercept, and adalimumab more effective than infliximab." (PMID 24489444, 2013). "Furthermore, TNF inhibition has been most successful in rheumatoid arthritis, not so in multiple sclerosis and its effect remains currently to be fully assessed in PD." (PMID 22548201, 2012). "TNF-α, IL-6 and LIF also contribute to tissue erosion in advanced stages of OA, although their implication in rheumatoid arthritis (RA) prevails." (PMID 22051322, 2011). "Rheumatoid Arthritis drugs recommended by The American College of Rheumatology (ACR) fall into several categories: small molecule DMARDs including methotrexate, lefluonamide and others; anti-TNF-α agents; T-cell activation modulators; IL-6 antagonists; IL-1 antagonists; and B-cell directed therapy." (PMID 21423713, 2011). "National Institute of Clinical Excellence (NICE) guidelines (TA130), which were in place during the evaluation stated that patients with rheumatoid arthritis would not be able to try a second TNF inhibitor if their first attempt failed, unless therapy was withdrawn due to an adverse event." (PMID 21672203, 2011). "However, for particular subsets of rheumatoid arthritis patients, TNF-α blockade does not appear to relieve the symptoms of RA." (PMID 21423713, 2011). "Biologic agents that target tumor necrosis factor (TNF), B cells, T cells, or, most recently, interleukin-6 (IL-6) have emerged as effective treatments for patients with rheumatoid arthritis (RA)." (PMID 21884601, 2011). "ML120B has been shown to inhibit tumor necrosis factor-α (TNF-α)-induced nuclear translocation of p65 subunit of NF-κB and block TNF-α-stimulated cytokine production in human fibroblast-like synovial cell cultures isolated from patients with rheumatoid arthritis." (PMID 20809973, 2010). "TNF-α for instance, activates preferentially the MAPK-p38 isoform p38α in synovial macrophages and synovial fibroblasts (RASFs) in rheumatoid arthritis (RA)." (PMID 20955562, 2010). "It is known that pro-inflammatory cytokines such as IL-1β or TNFα stimulate HMGB1 translocation into the cytoplasm and release in different cell types, although TNFα is not the main inducer of extracellular HMGB1 during synovitis in rheumatoid arthritis patients." (PMID 20799933, 2010). "PBL were perfused over HUVEC that had been cultured with fibroblasts isolated from the inflamed synovium or the skin of patients with rheumatoid arthritis or osteoarthritis, or from normal synovium, with or without exposure to the inflammatory cytokines TNF-α+IFN-γ." (PMID 19130557, 2009).
rheumatoid arthritis (continued). "Chronic inflammatory diseases such as rheumatoid arthritis (RA), asthma, inflammatory bowel disease (IBD), and multiple sclerosis still pose a large unmet medical need despite recent therapeutic advances such as inhaled steroids (asthma) or TNFα antagonists (RA and IBD)." (PMID 16772045, 2006). "TNF may also directly affect neovascularisation and angiogenesis by upregulating factors such as VEGF as previously shown in human macrophage cells and synovial cells from rheumatoid arthritis patients." (PMID 15026813, 2004). "Moreover, the levels of TNF-α and IL-6 are elevated not only in COM but also in other chronic inflammatory conditions like psoriatic arthritis (PsA) and rheumatoid arthritis (RA)." (PMID 40595978, 2025). "In patients with OA, the immunoexpression levels of TNF-α, IL-1β, IL-7, MMP-1, MMP-2, and MMP-3 were significantly higher in patients with active rheumatoid arthritis (RA), whereas the immunoexpression levels of IL-1, IL-2, IL-4, IL-6, IL-15, IL-18, and MMP-3 were not statistically different." (PMID 40004793, 2025). "In autoimmune diseases like rheumatoid arthritis (RA) and systemic lupus erythematosus (SLE), inflammatory signals such as TNFα and IL-6 lead to epigenetic reprogramming of SEs, resulting in the aberrant overexpression of pro-inflammatory cytokines such as TNF, IL1 family, and chemokines." (PMID 40895527, 2025). "TNF-α inhibitors, which neutralize the activity of TNF-α, have traditionally been reserved for pregnant women with autoimmune conditions such as rheumatoid arthritis (RA) or inflammatory bowel disease (IBD)." (PMID 39597081, 2024). "However, exercise has been shown to enhance muscle mass and decrease levels of inflammatory markers, such as TNF-α, C-reactive protein (CRP), and IL-6, in patients with rheumatoid arthritis (RA)." (PMID 38822418, 2024). "Interleukin-1 (IL-1), interferon-γ (IFN-γ), and tumor necrosis factor-α (TNF-α) were among the pro-inflammatory cytokines that were reduced by blocking FKN-CX3CR1 interaction, suggesting that this pathway could be a target for the therapy of rheumatoid arthritis." (PMID 38658971, 2024). "Similarly, another systematic review with meta‐analysis found significant reductions in the ESR and a trend toward a reduction in TNF‐α plasma levels after nonsurgical periodontal treatment, concluding that nonsurgical periodontal treatment can benefit patients with rheumatoid arthritis." (PMID 39494478, 2024). "Notably, specific interventions such as anti-TNF therapy for mild anemia in conditions like inflammatory bowel disease and rheumatoid arthritis have not been explored in the context of HIV-related mild anemia, representing a potential area for future investigation." (PMID 38675885, 2024). "Furthermore, TNF plays a central role in autoimmune diseases such as rheumatoid arthritis (RA), inflammatory bowel diseases (IBD), and systemic lupus erythematosus, where anti-TNF therapy has been clinically applied." (PMID 38540714, 2024). "Anti-tumor necrosis factor-alpha (anti-TNF-alpha) agents have permanently modified the landscape of therapeutic options in multiple chronic auto-inflammatory diseases such as inflammatory bowel diseases (IBD), rheumatoid arthritis (RA), and psoriasis." (PMID 39311378, 2024). "In rheumatoid arthritis (RA), HOTAIR overexpression reduced the secretion of IL-23 and IL-17, and decreased the number of pro-inflammatory cells (Th17), as well as diminishing levels of IL-1β, phospho-p65, and TNF-α in cartilage." (PMID 37190068, 2023). "ADL is a fully human anti-TNF mAb IgG1 approved for ankylosing spondylitis (AS), Crohn’s Disease (CD), juvenile idiopathic arthritis (JIA), psoriatic arthritis (PsA), psoriasis (Ps), rheumatoid arthritis (RA), and urticarial vasculitis (UV)." (PMID 37176711, 2023).
rheumatoid arthritis (continued). "On the contrary, in TNFα-induced rheumatoid arthritis mice that do not express sclerostin (SOST knock-out mice or after antisclerostin antibody administration), a rapid deterioration of rheumatoid arthritis occurred, suggesting that sclerostin may have a protective role." (PMID 35160258, 2022). "The aim of this study is to examine the impact of tumor necrosis factor inhibitors (TNFI) on nontuberculous mycobacterium (NTM) infection in rheumatoid arthritis (RA) patients in a mycobacterium tuberculosis (MTB) endemic area." (PMID 35256729, 2022). "Furthermore, it has been shown that bispecific anti-TNF-α/IL-17 antibodies may have superior efficacy and safety in treating rheumatoid arthritis, but this has not been demonstrated in another study involving patients with psoriasis arthritis." (PMID 36483564, 2022). "Here, we conducted a meta-analysis on the publicly available gene expression cDNA microarray datasets that examine the differential expression observed in response to anti-TNFα therapy with psoriasis (PsO), inflammatory bowel disease (IBD) and rheumatoid arthritis (RA)." (PMID 35627163, 2022). "Furthermore, overexpression of IL-6, IL-10, IL-17, and TNF-α, among others, is important in the pathogenesis of SLE, polymyositis (PM), dermatomyositis (DM) and rheumatoid arthritis (RA) and is significantly related to disease activity." (PMID 33882880, 2021). "Tumor necrosis factor inhibitors (TNFi) are widely used for the treatment of patients with rheumatoid arthritis (RA), who do not respond to conventional synthetic disease-modifying antirheumatic drugs (csDMARDs)." (PMID 34222289, 2021). "Biological disease-modifying antirheumatic drugs (bDMARDs), such as tumor necrosis factor (TNF) inhibitors, are recommended for the treatment of rheumatoid arthritis (RA) when disease activity remains moderate or high despite conventional synthetic DMARD (csDMARD) monotherapy." (PMID 33546755, 2021). "Additionally, it has been proposed that TNF-α-induced IL-6 and IL-8 production in FLS from patients with rheumatoid arthritis (FLS-RA) is dependent on L-lactate levels." (PMID 35095895, 2021). "At present, the clinical treatment of rheumatoid arthritis drugs mainly include nonsteroidal anti-inflammatory drugs (NSAIDs), disease-modifying antirheumatic drugs (DMARDs), steroid hormones, and biological agents (TNF-α antibody and TNF-α receptor inhibitor)." (PMID 32063980, 2020). "Furthermore, the proinflammatory cytokines IL-6, TNF-α, IFN-γ, and IL-12 play such an important inductor of inflammation in disorders such as severe/uncontrolled asthma, Alzheimer's disease, and rheumatoid arthritis and may be considered a predictive factor for treatment failure." (PMID 32351323, 2020). "HIF-1α acts as a key regulator during inflammation, increasing pro-inflammatory cytokines (e.g., TNF-α, IL-1β, IL-6, and IL-8), matrix metalloproteinases (e.g., MMP-1, MMP-3, and MMP-9), and pathways of glucose metabolism in rheumatoid arthritis (RA)." (PMID 33374961, 2020). "Previously, we demonstrated in test and validation cohorts that type I IFN (T1IFN) activity can predict non-response to tumor necrosis factor inhibitors (TNFi) in rheumatoid arthritis (RA)." (PMID 32765497, 2020). "Indeed, tumor necrosis factor inhibitors (anti-TNF), the biologic DMARDs most often used in JIA, rheumatoid arthritis (RA), and inflammatory bowel disease, are the drug class that accounted for the highest proportion of public drug spending in Canada in 2018." (PMID 32192528, 2020). "It has previously been shown that TNF antagonism (anti-TNF) is a successful therapeutic option that has been applied in various inflammatory cases, including inflammatory bowel disease (IBD), spondyloarthritis (SpA), psoriasis, and rheumatoid arthritis (RA)." (PMID 31239840, 2019).